DCTN6 (dynactin subunit 6)
Description:
Part of the dynactin complex that activates the molecular motor dynein for ultra-processive transport along microtubules.
Synonyms: WS3; WS-3; p27
Tractability: PROTAC: ubiquitination databases record sites on it; its protein half-life has been measured.
Gene: Protein-coding gene on chromosome 8 (30,156,319 to 30,183,639, forward strand). Ensembl gene ENSG00000104671.
Subcellular location: Cytoplasm, cytoskeleton; Chromosome, centromere, kinetochore
Subcellular location (Human Protein Atlas): Cytosol
Pathways (Reactome):
Vesicle-mediated transport: COPI-independent Golgi-to-ER retrograde traffic; COPI-mediated anterograde transport
Cellular responses to stimuli: HSP90 chaperone cycle for steroid hormone receptors (SHR) in the presence of ligand
Immune System: MHC class II antigen presentation
Gene Ontology:
Molecular function: dynein complex binding
Biological process: mitotic spindle organization
Cellular component: centrosome; cytosol; dynactin complex; cytoskeleton
Genetic constraint (gnomAD): Loss-of-function variants: 3 observed, 13.48 expected, observed/expected ratio (o/e) 0.22, 90% interval 0.1 to 0.57. The upper end of that interval is the gene's LOEUF score, 0.57, which puts it in group 2 of 6, group 1 being the genes least tolerant of losing a copy. Missense variants: 152 observed, 186.56 expected, observed/expected ratio (o/e) 0.81, 90% interval 0.71 to 0.93. Synonymous variants: 49 observed, 66.65 expected, observed/expected ratio (o/e) 0.74, 90% interval 0.58 to 0.93.
Homologues: Orthologues: macaque DCTN6 (100% identical), guinea pig DCTN6 (98% identical), pig DCTN6 (98% identical), dog DCTN6 (98% identical), chimpanzee DCTN6 (96% identical), mouse Dctn6 (96% identical), rat Dctn6 (94% identical), rabbit DCTN6 (87% identical), tropical clawed frog dctn6 (85% identical), Drosophila melanogaster DCTN6-p27 (47% identical), Caenorhabditis elegans dnc-6 (38% identical).
Diseases named in the same sentence as DCTN6 in open-access papers:
DCTN6 is named in the same sentence as 8 diseases in open-access papers, as found by Europe PMC text mining. Sharing a sentence is not in itself a finding about the gene and the disease. The quoted sentences say what the papers report.
Alzheimer disease (1 paper, 2023). A progressive, neurodegenerative disease characterized by loss of function and death of nerve cells in several areas of the brain leading to loss of cognitive function such as memory and language. "Interestingly, RTN3-immunoreactive dystrophic neurites have been found in Alzheimer’s disease brains, and DCTN6 deficiency enhanced RTN3 protein level and the formation of RTN3-immunoreactive dystrophic neurites in the hippocampus of aging mice." (PMID 36879021, 2023).
glioma (1 paper, 2022). A benign or malignant brain and spinal cord tumor that arises from glial cells (astrocytes, oligodendrocytes, ependymal cells). "DCTN6 has high expression in low-grade glioma but it is associated with unfavorable survival outcomes." (PMID 35281472, 2022).
melanoma (1 paper, 2008). A malignant, usually aggressive tumor composed of atypical, neoplastic melanocytes. "The genes detected as down-regulated in most metastatic melanomas, and that are therefore candidates for metastasis suppressors, are LUM (lumican), DCTN6 (dynactin 6) and DNCI2 (dynein intermediate chain 2)." (PMID 18211678, 2008).
Obesity (1 paper, 2022). Accumulation of substantial excess body fat. "Overall, the upregulation of MIR222 could not only inhibit the expression of tumor suppressors such as target genes DIRAS3 and DCTN6 in prostate cancer but also prove that obesity has a strong correlation with cancer metastasis." (PMID 35164166, 2022).
tumor (2 papers, 2022 to 2025). "Conversely, DCTN4 and DCTN6 were both observed to be downregulated in tumor tissues of OC compared with adjacent tissues in this study." (PMID 35281472, 2022). "The Wilcoxon rank-sum test showed that ALG8 (P < 0.001) had a higher expression level in tumor tissues compared with normal tissues, while DCTN4 (P < 0.001), DCTN6 (P < 0.001), and UBB (P < 0.001) had lower expression levels in tumor tissues." (PMID 35281472, 2022). "Additionally, we found that essential passenger genes, including NOP2, DCTN6 and FOXD4, were associated with closed chromatin and increased DNA methylation at the same respective loci when amplified compared to when not amplified in tumor PDCs compared to normal PDCs." (PMID 40931149, 2025).
cancer (1 paper, 2022). A tumor composed of atypical neoplastic, often pleomorphic cells that invade other tissues. "Moreover, with the low expression of TF RBMX, it could upregulate miRNA MIR222 for the purpose of downregulating the downstream target genes DIRAS3 and DCTN6, enhancing cancer cell proliferation, cell survival rate, and inducing invasion." (PMID 35164166, 2022). "Eventually, low expression of target genes DCTN6 and DIRAS3 enhance cancer cell proliferation and cell survival rate, and accelerate cancer cell invasion." (PMID 35164166, 2022).
DCTN6 also shares sentences with these, for which no sentence is quoted: ovarian carcinoma (1 paper); prostate carcinoma (1).